CXCL5 (C-X-C motif chemokine ligand 5)
Diseases named in the same sentence as CXCL5 in open-access papers (continued):
Sharing a sentence is not in itself a finding about the gene and the disease.
non-small cell lung carcinoma (19 papers, 2008 to 2025). A group of at least three distinct histological types of lung cancer, including non-small cell squamous cell carcinoma, adenocarcinoma, and large cell carcinoma. "Interestingly, SOX2-induced expression of CXCL5 was previously linked to neutrophil recruitment in non-small-cell lung cancer." (PMID 38225383, 2024). "CXCL5 has been reported to enhance angiogenesis in human non-small cell lung cancer (NSCLC) by a cyclooxygenase (COX-2)- dependent mechanism." (PMID 40852716, 2025). "Multiple studies have observed that CXCL5 is overexpressed in non-small cell lung cancers (NSCLCs) and its expression was correlated with unfavorable prognosis in patients with NSCLC." (PMID 36612163, 2022). "It has been reported that CXCR2+ neutrophils are recruited by CXCL5 in tumor tissues to promote tumor progression in liver and non-small cell lung cancers." (PMID 34659209, 2021). "Antibody neutralization of CXCL5 in experimental models of human non-small-cell lung cancer decreased tumor angiogenesis and metastasis." (PMID 30792394, 2019). "CXCL5 has been reported as an angiogenic factor in non-small cell lung cancer, where the protein level of CXCL5 is positively correlated with tumor vessel density." (PMID 23991127, 2013). "For example, the directional migration of A2056 human melanoma cells was shown by exposure of the C-X-C-type chemokine ligand (CXCL) 8, and both CXCL8 and CXCL5 expression in non-small cell lung carcinoma (NSCLC) has been correlated with tumor angiogenesis." (PMID 22952881, 2012). "Interestingly, CXCL5 expression in non-small cell lung cancer was related to a reduced survival rate." (PMID 37021054, 2023). "The reason might be that they only evaluated the prognostic value of CXCL5 in early stage non-small cell lung cancer (stages I and II)." (PMID 29743818, 2018). "In addition to its crucial involvement in MDSC recruitment, it has been reported that CXCL5 overexpression in non-small cell lung cancer (NSCLC) enhances both tumor growth and angiogenesis by a cyclooxygenase (COX-2) dependent mechanism, whereas its depletion attenuates this phenotype." (PMID 30591657, 2018). "It has also been reported that IL-17 augments the secretion of an array of angiogenic CXC chemokines, including CXCL1, CXCL5, CXCL6, and CXCL8 by three different non-small cell lung cancer cell lines." (PMID 23665907, 2013). "Involvement of CXCL5 has also been reported in different neoplastic processes with major focus on non small cell lung cancer (NSCLC), where CXCL5 was shown to be an important angiogenic factor." (PMID 18578857, 2008). "Tumor-derived CXCL5 can promote human CRC metastasis by activating ERK/Elk-1/Snail and AKT/GSK3β/β-catenin pathway, accelerate osteosarcoma growth and can serve as a biomarker for non-small cell carcinoma, etc.." (PMID 33240582, 2020).
diabetes (18 papers, 2009 to 2026). "Serial in vitro and in vivo experimental models were used to evaluate if direct inhibition by neutralizing antibody or deficiency of CXCL5 by genetic knockout could improve diabetes related vasculopathy." (PMID 37420254, 2023). "Higher chemokine C-X-C motif ligand 5 (CXCL5) level was observed in type 2 diabetes mellitus (DM) patients; however, its role in diabetic vasculopathy was not clarified." (PMID 37420254, 2023). "We observed enrichment in disease ontologies relating to acquired metabolic disease, glucose metabolism disease, diabetes mellitus, carbohydrate metabolism disease, disease of metabolism, and clustering around genes including CXCL5, EGF, and SPARC." (PMID 36138412, 2022). "We show that inhibition of theCXCL5-CXCR2 axis, both by CXCR2 antagonists or CXCL5 blocking antibodiesdecreases glycemia in mice models of diabetes." (PMID 20157549, 2009). "While both MIP-1β and CXCL5 and probably other chemokines may impair angiogenesis in diabetes, the specific in vivo anti-inflammatory effects via CXCL5 suppression can be further elucidated in future." (PMID 37420254, 2023). "Metformin, as a well-known drug for diabetes, can inhibit SASP by decreasing the expression of IL-1β, IL-6, C-X-C motif chemokine 5 (CXCL5) and NF-kB." (PMID 36744145, 2023). "Exposure of cultured podocytes to AGE, a diabetes-like condition, increased JAK2 activity and induced expression of SAA3 as well as pro-inflammatory mediators including Cxcl5, Ccl2, and Ccl5." (PMID 30763329, 2019). "On the other hand, some diabetes medications, like the dipeptidyl peptidase-4 inhibitor sitagliptin, suppress CXCL5 and do not hasten the development of intestinal neoplasia in mice." (PMID 38884019, 2024). "Importantly, even after glucose control in diabetics, the macrophage is dysfunctional in these patients, exhibiting M1 pro-inflammatory phenotype and elevated levels of inflammatory chemokines CXCL1, CXCL5, and RANTES12." (PMID 35957939, 2022). "In conclusion, the results of our study suggest that increased spinal levels of CXCL1, CXCL5, CXCL9, or CXCL12 protein in mice after STZ treatment may participate in the development of diabetic neuropathic pain." (PMID 25789329, 2015). "Theoretically, CXCL5 might contribute to the vascular complications in diabetes, though the direct link and detailed mechanism were not yet established." (PMID 37420254, 2023).
asthma (16 papers, 2009 to 2025). "Many genes, including Il33, Cxcl5, Cxcl15, Ccl20, Cxcl3, Cxcl1, C3, and Pfn1, which have been linked to asthma pathogenesis, showed a cell type-specific response to HDM." (PMID 35627266, 2022). "The airway epithelium expresses CCL2, CCL3, CCL4, CCL5, CCL11, and CXCL5, which are associated with asthma." (PMID 35743888, 2022). "Neutrophilic inflammation, often associated with severe or steroid-resistant asthma, is driven by distinct pathways involving IL-8, GM-CSF, and chemokines like CXCL1 and CXCL5." (PMID 41259396, 2025). "CXCL5 regulates neutrophil trafficking to the lung via CXCR2 and has been implicated in asthma and multiple cancers." (PMID 38355791, 2024). "While CXCL1, CXCL2, and CXCL5 gene transcripts were shown to be elevated in a mouse model of severe asthma, treatment with Ruxolitinib, an anti-inflammatory drug and powerful inhibitor of janus kinase 1/2 (JAK1/2), caused the upward spiraling to be reversed." (PMID 36164329, 2022). "Gene transcripts of some of these chemokines (CXCL1, CXCL2, and CXCL5) were found to be upregulated in a mouse model of severe asthma." (PMID 36164329, 2022). "Some highly significant genes in the microarray analysis also relevant to asthma (Ccl2, Ccl11, Ccl24 and Cxcl5) were further confirmed by quantitative PCR." (PMID 25318534, 2014). "Thus exposure to HDM allergens may alter ENA-78/CXCL5 levels in the lungs and may affect angiogenesis and the inflammatory response in the airways of asthma patients." (PMID 24883064, 2014). "Our study found that Dectin-1/caspase-11 activation in asthma is not only related to CXCL1, but also related to the secretion of CXCL3 and CXCL5." (PMID 38459541, 2024). "Therefore, our study suggested that Dectin-1/caspase-11-mediated macrophage pyroptosis promotes neutrophil airway infiltration in asthma, which depends on the secretion of chemokines such as CXCL1, CXCL3 and CXCL5." (PMID 38459541, 2024). "Few studies of human disease have investigated the biological role of CXCL6; however, ortholog CXCL5/ENA78 is involved in a variety of inflammatory diseases such as ARDS, acute coronary syndromes, inflammatory bowel disease, asthma, and psoriasis, diseases known to have a neutrophil component." (PMID 26617980, 2015).
colon carcinoma (16 papers, 2017 to 2025). "Neutralization of CXCL5 markedly attenuated cachexia development in animal models, including a human colon carcinoma xenograft." (PMID 41392310, 2025). "Patient colon tumor tissue immunostaining revealed that areas of CXCL5 expression occur within the CAF-rich stromal compartment, as shown by colocalization with vimentin." (PMID 41392310, 2025). "CXCL5 neutralization inhibited cachexia in mice co-injected with HCT 116 colon cancer cells and CAF." (PMID 41392310, 2025). "The occurrence and distribution of CXCL5 expression in human tumors was investigated in samples obtained from patients that underwent tumor resection surgery for colon cancer." (PMID 41392310, 2025). "Overexpression of S100A8/S100A9 in mouse colon cancer cells CT26.WT led to differential increases in the secretion levels of various cytokines (CXCL5, CXCL11, GM-CSF, G-CSF, IL1a, IL1b, sTNF RI, and CCL3)." (PMID 38817853, 2024). "We discovered that the expression of S100A8 in colon cancer cells led to increased levels of CXCL5 and its corresponding receptor, CXCR2." (PMID 38817853, 2024). "CXCL5 can promote colon cancer metastasis by activating the ERK/Elk‐1/Snail and AKT/GSK3β/β‐catenin signaling pathways." (PMID 37666495, 2024). "In conclusion, our findings offer compelling evidence that S100A8 amplifies the proliferative and invasive properties of colon cancer cells by activating the CXCL5/CXCR2 pathway." (PMID 38817853, 2024). "S100A8 facilitates colon cancer cell proliferation, invasion, and metastasis through the CXCL5/CXCR2 biological axis." (PMID 38817853, 2024). "We also showed that these two chemokines but also CXCL3 and CXCL5 were more expressed in tumors of patients with colon cancer as compared to healthy tissue." (PMID 29983866, 2018). "Considering that the tumor monocyte population decreased upon EGC depletion, we speculate that CRC EGC-derived chemokines (i.e., CCL2 and CXCL5) could also promote the infiltration of monocytes in the colonic tumor site." (PMID 39030280, 2024). "Inhibitor experiments confirmed our hypothesis, validating that S100A8 enhances the proliferation of colon cancer cells and boosts their invasive metastatic potential through the CXCL5/CXCR2 bioaxis pathway." (PMID 38817853, 2024). "Moreover, S100A8 enhances the proliferation and invasion of colon cancer cells, mediated by the chemokine CXCL5 and its receptor CXCR2." (PMID 38817853, 2024). "Immunodeficient mice were transplanted with human colon cancer cells plus CAF and treated with a CXCL5 neutralizing antibody." (PMID 41392310, 2025). "Combining the expression trends of these genes in colon cancer and after aspirin treatment, we found that aspirin further upregulated NOX4, CXCL8, CXCL5, LIF, GDF15, and MMP13, while stimulated inhibition of IL2, NCF1, and PTGS1." (PMID 41425852, 2025). "CXCL5, a neutrophil chemokine, is upregulated in PIK3CA-mutant mouse colon cancer cells through the NF-κB pathway." (PMID 38194275, 2024). "The specific receptor for CXCL5 is CXCR2, which is overexpressed in cancers with high metastatic potential, such as breast, lung, and colon cancer cells." (PMID 37015905, 2023). "Tumor progression-enhancing effects of CXCL7 and CXCL5 on CCA cells were described, in contrast, it has also been reported that CCL14 inhibited the proliferation and invasion of colon cancer cells." (PMID 35377900, 2022). "We found that the expression levels of some genes enriched in IL-11+ fibroblasts, including Wnt5a, Mmp13, Timp1, Il1rl1, Cxcl5, Saa3, Inhiba, Ascl4, and Tnfrsf11b, were elevated in mouse AOM/DSS-induced colon tumor tissues." (PMID 33863879, 2021). "Colon cancer patients with upregulated NOX4, CXCL8, CXCL5, GDF15, or MMP13 may not benefit from aspirin chemoprophylaxis." (PMID 41425852, 2025).
glioma (16 papers, 2016 to 2025). A benign or malignant brain and spinal cord tumor that arises from glial cells (astrocytes, oligodendrocytes, ependymal cells). "Emerging role of CXCL5 is found in glioma biology since its expression has been linked with poor patient prognosis and, in vitro, CXCL5 increased migration and proliferation of the glioblastoma cell line U87." (PMID 33066172, 2020). "Our results demonstrated a correlation between high levels of WDHD1 expression and positive CXCL10 and CXCL5 in gliomas." (PMID 38980253, 2024). "The fold change of the CXCL5 gene was observed to be relatively higher in the plasma samples of glioma patients compared to healthy controls." (PMID 34643804, 2022). "For example, SOX15 is related to pancreatic tumors, esophagus tumors and embryonal cell carcinoma, while CXCL5 is related to laryngeal cancer and glioma and TLX1 is related to leukemia." (PMID 34691933, 2019). "Therefore, the correlative molecular markers and molecular mechanisms should be explored to assess the occurrence and treatment of glioma.WB and qPCR assays were used to detect the expression of CXCL5 in human GBM tissues." (PMID 38287266, 2024). "Another example of analysis is CXCL2 and CXCL5 in brain lower grade glioma." (PMID 37686093, 2023). "In parallel, glioma-associated macrophages are stimulated by glioma cells to produce tumor necrosis factor-α (TNFα), which activates the endothelial cell expression of the proangiogenic molecules (VCAM-1, ICAM-1, CXCL5, and CXCL10)." (PMID 35740307, 2022). "In previous research, CXCL5 was shown to be up-regulated in glioma tissues compared with normal brain tissues and could promote the proliferation and migration of glioma cells by activating the ERK, JNK, p38, and MAPK signaling pathways." (PMID 33429364, 2021). "Recent studies have reported that CXCL5 might promote migration and invasion in autocrine- and paracrine-dependent manners in glioma and osteosarcoma cells." (PMID 29665837, 2018). "CXCL5 promotes the proliferation and migration of glioma cells." (PMID 28744466, 2017). "Neutrophils are recruited to glioma inflammatory regions by chemokines such as CXCL1, CXCL2, CXCL3, CXCL5, CXCL6, IL-8 (CXCL8), and IL-1β, which are secreted by glioma cells." (PMID 41272822, 2025). "These tumors are lower grade glioma (in the case of CXCL3 and CXCL5) and diffuse large B-cell lymphoma (in the case of CXCL2 and CXCL3)." (PMID 37686093, 2023). "The exception was brain lower-grade glioma, where higher CXCL1 expression correlated with worse prognosis, while CXCL2 and CXCL5 expression correlated with better outcomes." (PMID 37686093, 2023). "In glioma cells, CD133, a cancer stem cell marker, raises the expression of IL-1β and its downstream chemokines, including CCL3, CXCL3, and CXCL5." (PMID 33429364, 2021). "The results showed that there were trends linking these cytokines, CCL20, CXCL1, CXCL2, CXCL5, and CXCL16, to ADO expression in gliomas but these correlations were not significant, probably due to the low number of patients recruited to the study." (PMID 33483477, 2021). "The original RNA-seq results suggested that glioma patients have higher levels of CCL20, CXCL1, CXCL2, CXCL5, and CXCL16 compared to noncancerous patients and that the levels of these small chemotactic cytokines in glioma are correlated with malignancy." (PMID 33483477, 2021).
renal cell carcinoma (14 papers, 2015 to 2025). "It has been shown that the increase of CXCL5 cytokines is associated with sunitinib resistance in renal cell carcinoma." (PMID 34187413, 2021). "Soluble CD163, CXCL5, and blood cell counts, including absolute lymphocyte and eosinophil counts, were identified as predictors of irAEs in melanoma, renal cell carcinoma (RCC), and urothelial carcinoma." (PMID 41239350, 2025). "In renal cell carcinoma, androgen receptor mediated CXCL5 signaling activates the AKT/NF-κB pathway to facilitate angiogenesis." (PMID 38343536, 2024). "IL-8 and CXCL5 secreted by renal cell carcinoma (RCC) cells have been shown to recruit neutrophils and abrogate the formation of metastases supporting the anti-tumor role of neutrophils." (PMID 37376417, 2023). "A previous study indicated that PTEN blocked the CXCL5 expression in renal cell carcinoma." (PMID 39765818, 2024). "In this respect, the secretion of CXCL5 and IL-8 by renal cell carcinoma (RCC) cells recruited neutrophils and inhibited the formation of metastases." (PMID 33105656, 2020). "While CXCL5 and/or CXCR2 are increased in patients with renal cell carcinoma, type-2 diabetic nephropathy, or acute rejection of kidney allograft, the role of CXCL5 in mediating continually declining kidney function is not clear." (PMID 35723372, 2022). "In patients with renal cell carcinoma (RCC), CXCL5 levels were positively correlated with neutrophil numbers and immature MDSC counts." (PMID 34503058, 2021). "In addition, CXCL5, IL4 may be involved in the regulation of the immune microenvironment in renal cell carcinoma." (PMID 34187413, 2021).
rheumatoid arthritis (14 papers, 2013 to 2024). A chronic, systemic autoimmune disorder characterized by inflammation in the synovial membranes and articular surfaces. "Studies have shown that the expression level of CXCL5 is significantly upregulated in various inflammatory diseases, such as rheumatoid arthritis, inflammatory bowel disease, kidney diseases and liver ischemia–reperfusion injury." (PMID 38168591, 2024). "The Enrichr pathway assignment analysis (KEGG 2021 Human database) additionally revealed enrichment of chemokine encoding genes (CXCL1, CXCL2, CXCL3, CXCL6, CXCL5, CXCL8, CCL2) which were aligned to several pathways like amoebiasis and rheumatoid arthritis." (PMID 35646693, 2022). "CXCL5 is a biomarker of Th17-mediated autoimmune diseases, such as multiple sclerosis, rheumatoid arthritis, and pemphigus vulgaris, and sCD163 is an activation marker for CD163+ TAMs that appears in the serum as a result of proteolytic shedding." (PMID 29050354, 2017). "Macrophage-derived angiogenic chemokines identified in rheumatoid arthritis synovial tissue include ENA-78/CXCL5, a chemokine involved in the chemotaxis of neutrophils." (PMID 23725043, 2013). "Notably, CXCL5 is a biomarker of T helper 17 cell-mediated autoimmune diseases such as multiple sclerosis, rheumatoid arthritis, and pemphigus vulgaris; and soluble CD163 (sCD163) is a TAM marker that appears in the serum as a result of proteolytic shedding." (PMID 29643991, 2018). "Indeed, the serum levels of CXCL5 correlate with autoimmune diseases such as multiple sclerosis, rheumatoid arthritis, glomerulonephritis, pemphigus vulgaris, and bullous pemphigoid with several inflammation factors, though the main sources of CXCL5 is not fully investigated in each reports." (PMID 29643991, 2018). "Previous studies have shown that CXCL5 has a strong effect on neutrophil recruitment and is involved in a variety of inflammatory diseases, such as rheumatoid arthritis (RA) and pediatric ulcerative colitis, yet its role in AS remains unknown." (PMID 30804325, 2019).
bladder cancer (13 papers, 2018 to 2025). "The CXCL5 gene may induce bladder cancer recurrence by activating NF-kB pathway-regulated EMT that causes chemoresistance in bladder cancer cells." (PMID 37588995, 2023). "Exons 2 and 16 of DHTKD1 transcripts were back-spliced to develop circDHTKD1 that can promote lymphatic metastasis of bladder cancer by upregulating CXCL5." (PMID 38139387, 2023). "The CXCL5/CXCL2 axis also promotes bladder cancer cell migration by upregulating MMP2/MMP9, which is an Akt-dependent pathway." (PMID 37373052, 2023). "Several of the individual genes upregulated by Gardnerella exposures are involved in epithelial to mesenchymal transition (Cxcl5, Cxcr2, Tff1) or known to be elevated during squamous metaplasia or bladder cancer (Anxa10, Fosl1, Krt6a, Mmp10)." (PMID 35782131, 2022). "In bladder cancer, CXCL5 was found to be significantly upregulated and the CXCL5/CXCR2 axis could promote the migration and invasion of bladder cancer cells by activating the PI3K/AKT-induced upregulation of MMP2/MMP9." (PMID 29743818, 2018). "In bladder cancer, circDHTKD1 recruited and activated neutrophils by inducing CXCL5 expression, and then neutrophils participated in lymphangiogenesis by secreting VEGF-C, facilitating lymphatic metastasis of bladder cancer cells." (PMID 36797245, 2023).